JDP2 (Jun dimerization protein 2)
Diseases named in the same sentence as JDP2 in open-access papers (continued):
Sharing a sentence is not in itself a finding about the gene and the disease.
leukemia (3 papers, 2018 to 2025). A malignant (clonal) hematologic disorder, involving hematopoietic stem cells and characterized by the presence of primitive or atypical myeloid or lymphoid cells in the bone marrow and the blood. "Notably, IRF2BP2 was recently shown to interact and repress the function of the AP1 heterodimer ATF7/JDP2 in leukemia cells." (PMID 39752494, 2025). "In Tg(rag2:jdp2) fish, the kidney marrow was massively infiltrated with blast cells with a monomorphic appearance and high nuclear-to-cytoplasmic ratio, whereas blast cells were readily detectable on peripheral blood smears, indicative of leukemia." (PMID 29941549, 2018). "To test whether tumors from Tg(rag2:jdp2) zebrafish harbor leukemia-initiating cells, we exploited a recently developed immune-compromised zebrafish line with a rag2E450fs hypomorphic allele, which is permissive of adoptive transfer of allogeneic zebrafish cells." (PMID 29941549, 2018).
lung carcinoma (3 papers, 2015 to 2022). "In the lung cancer model, we also observed the potentiation of tumor growth in mice lacking JDP2." (PMID 26497998, 2015).
myocardial infarction (3 papers, 2018 to 2025). Gross necrosis of the myocardium, as a result of interruption of the blood supply to the area, as in coronary thrombosis. "Thus, FMN1, RNASE1 and JDP2 expression are promising candidates for the risk stratification of patients to develop HF after myocardial infarction." (PMID 29769710, 2018). "The first report about the association of increased JDP2 expression after myocardial infarction (MI) with HF progression was published by Maciejak and coworkers in 2015." (PMID 33923401, 2021). "In recent years, JDP2 has been identified as a potential prognostic marker for HF development after myocardial infarction." (PMID 33923401, 2021). "Interestingly, in humans enhanced expression of JDP2 after myocardial infarction correlated with HF progression." (PMID 29769710, 2018). "Also, in other studies, elevated JDP2 levels are found after myocardial infarction." (PMID 40710332, 2025).
allergies (2 papers, 2022 to 2025). "Therefore, to prevent oxidation and antioxidation, drugs directed against Jdp2 may represent a way to target the control of apoptosis, allergy, and immune regulation, as part of an immunotherapy." (PMID 33723743, 2022).
cardiac hypertrophy (2 papers, 2018 to 2025). "Another argument for the protective role of JDP2 is the recent finding, that knock out of JDP2 promotes cardiac hypertrophy and dysfunction in response to pressure overload in mice." (PMID 29769710, 2018). "As recently shown by our group, paroxysmal AF in mice overexpressing JDP2 for 5 weeks was accompanied by prolongation of PQ-interval, cardiac hypertrophy, increased collagen expression, reductions in connexin 40 expression and calcium handling proteins, and the induction of pro-inflammatory markers." (PMID 40710332, 2025). "Comparing gene expression between mice with abrogated vs. prolonged JDP2 overexpression, the general decrease in mRNAs coding for calcium handling proteins, and the enhancement of marker genes for cardiac hypertrophy and fibrosis are striking, and highlight them as factors maintaining AF." (PMID 40710332, 2025). "Interestingly, in mice with prolonged JDP2 overexpression and paroxysmal AF, still cardiac hypertrophy and a decline in mRNA expression of connexins and calcium handling proteins were pertinent." (PMID 40710332, 2025). "Besides this impairment in ventricular function, atrial dilatation, ventricular hypertrophy, and fibrosis became evident in mice overexpressing JDP2 for 5 weeks." (PMID 29769710, 2018). "Development of myocardial hypertrophy, fibrosis and cardiac dysfunction could be observed under JDP2 overexpression." (PMID 29769710, 2018). "AF declines, and other detrimental cardiac parameters, like cardiac hypertrophy or prolongation of PQ- or QRS-times, are no longer detectable following the absence of JDP2 overexpression." (PMID 40710332, 2025).
colon cancer (2 papers, 2022 to 2023). "The acetylation-deficient mutant UHRF1 4 KR loses the ability to inhibit JDP2 and the latter gene will be upregulated to suppress colon cancer cell proliferation." (PMID 37701039, 2023). "Furthermore, upregulated JDP2 expression by acetylation-deficient mutant of UHRF1 might be an important epigenetic target for colon cancer cell proliferation." (PMID 35951156, 2022). "JDP2 gene is known as one of UHRF1 target genes that correlates with increased UHRF1 expression and promoter DNA methylation in colon cancer cells and also known for inhibiting cancer cell proliferation by repressing cell cycle progression." (PMID 35951156, 2022). "With transient transfection of UHRF1 WT and 4KR, the effects of UHRF1 4KR mutant on Jun dimerization protein 2 (JDP2) gene expression, cell proliferation and cell cycle were investigated by RT-qPCR and FACS analysis in shUHRF1 colon cancer cell line." (PMID 35951156, 2022). "JDP2 is a transcription repressor and is repressed by UHRF1 in colon cancer." (PMID 37701039, 2023).
depression (2 papers, 2019 to 2025). "In summary, through bioinformatics and machine learning approaches, we have identified histone acetylation-related biomarkers ALOX5, JDP2, and KPNB1 associated with depression." (PMID 40370665, 2025). "We therefore hypothesize that JDP2 may influence histone acetylation by modulating ROS levels, thereby playing a pivotal role in regulating depression-related genes." (PMID 40370665, 2025).
dilatation (2 papers, 2018 to 2021). "Already the first description of transgenic JDP2 mice with a continuous cardio-specific JDP2 overexpression from birth up to 4 weeks of age characterized JDP2 as a major mediator of massive bi-atrial dilatation." (PMID 33923401, 2021).
paroxysmal AF (2 papers, 2020 to 2025). "In conclusion, JDP2 overexpression causes atrial structural, pro-inflammatory and calcium handling remodeling, thus promoting the initiation of paroxysmal AF in mice." (PMID 33265909, 2020). "JDP2-overexpressing mice, therefore, represent a uniquely suited animal model for the investigation of mechanisms underlying the development of paroxysmal AF." (PMID 33265909, 2020). "In contrast to the situation in JDP2-overexpressing mice, however, RyR2 expression was increased in human paroxysmal AF." (PMID 40710332, 2025). "Similar to our previous findings, JDP2 overexpression provoked prolongation of the PQ interval and paroxysmal AF." (PMID 40710332, 2025). "After 5 weeks of JDP2 overexpression in adult mice leading to paroxysmal AF, overexpression of JDP2 was interrupted for another 5 weeks, and ECG recordings and expression analyses were performed." (PMID 40710332, 2025). "Cardiac-specific JDP2 overexpression for 5 weeks, resulting in paroxysmal AF, was either continued or repressed via a tet-off system for another 5 weeks." (PMID 40710332, 2025). "A decrease in ejection fraction and impaired contractile function of isolated ventricular cardiomyocytes were observed after only 1 week of JDP2 overexpression, while paroxysmal AF occurred after 5 weeks of JDP2 overexpression." (PMID 40710332, 2025). "For this reason, we have demonstrated here that JDP2 overexpression produces spontaneous paroxysmal AF under roaming conditions." (PMID 33265909, 2020). "ECG recordings were performed weekly, and after 4 and 5 weeks of JDP2 overexpression, periods of spontaneous paroxysmal AF were detected." (PMID 33265909, 2020). "Interestingly, all of the substantial alterations in calcium handling proteins observed in JDP2-overexpressing mice were completely reversible upon abrogation of JDP2 overexpression, as were the episodes of paroxysmal AF." (PMID 40710332, 2025). "We now investigated whether AF and atrial remodeling will be reversible upon termination of JDP2 overexpression, and whether paroxysmal AF converts to permanent AF in the presence of maintained JDP2 overexpression." (PMID 40710332, 2025). "JDP2-overexpressing mice develop paroxysmal AF within 4–5 weeks in juvenile or adult mice." (PMID 40710332, 2025). "Furthermore, the maximum duration of paroxysmal AF in JDP2 mice 4 and 5 weeks after the start of JDP2 overexpression was less than 2 min." (PMID 33265909, 2020). "The main findings of this study are that paroxysmal AF, which develops under short-term (5 weeks) heart-specific JDP2 overexpression, does not turn into persistent AF under prolonged (10 weeks) JDP2 overexpression." (PMID 40710332, 2025). "In conclusion, atrial remodeling and paroxysmal AF under JDP2 overexpression are not sufficient to maintain or aggravate AF in the absence of JDP2." (PMID 40710332, 2025). "Extending JDP2 overexpression did not aggravate the AF phenotype, still paroxysmal AF, prolongation of PQ intervals, and atrial hypertrophy were present." (PMID 40710332, 2025). "Indeed, spontaneous paroxysmal AF was detected in 9 of 11 JDP2 mice 4 and 5 weeks after the start of JDP2 overexpression, whereas no episodes of AF were detected in WT mice (n = 10; p = 0.0002 vs. JDP2 mice, Fisher’s exact test)." (PMID 33265909, 2020).
T-cell leukemia (2 papers, 2016 to 2021). A malignant disease of the T-lymphocytes in the bone marrow, thymus, and/or blood.
acute myeloid leukaemia (1 paper, 2025). "Furthermore, ATF7 forms functional heterodimers (e.g., ATF7/JDP2) involved in modulating inflammatory pathways in acute myeloid leukaemia (AML), acting to counteract gene‐activating functions and suppress inflammatory overactivation." (PMID 40903840, 2025).
adrenocortical cancer (1 paper, 2017). "Herein, we show for the first time that JDP2 acts as a transcriptional activator of the Mc2r gene, including adrenocortical cancer cells." (PMID 28146118, 2017). "Moreover, overexpression of JDP2 in Y1 mouse adrenocortical cancer cells increases the level of melanocortin 2 receptor (MC2R) protein." (PMID 28146118, 2017). "However, more studies are needed to expand our understanding of how JDP2 coordinates with NR5A1 and FOXL2 to influence MC2R activity in adrenal glands and adrenocortical cancers." (PMID 28146118, 2017). "Indeed, we observed that overexpression of JDP2 enhances the level of MC2R, a critical and essential receptor for ACTH function, in mouse Y1 adrenocortical cancer cells." (PMID 28146118, 2017).
astrocytoma (1 paper, 2020). "In a previous global transcriptome study, we found that JDP2 is induced by CA, which is a phytochemical that activates both Nrf2 and ATF4 in U373MG human astrocytoma cells." (PMID 33108704, 2020). "Previously, we found that a stress‐responsive transcription factor, known as activating transcription factor 4 (ATF4), enhances JDP2 gene expression in human astrocytoma U373MG and cervical cancer HeLa cells; however, the role of JDP2 in the ATF4‐mediated stress response remained unclear." (PMID 33108704, 2020).
atrioventricular block (1 paper, 2020). A heart block that is initiated in the atrioventricular node. "The increase in PQ-interval is an indicator of prolonged atrioventricular conduction time, which significantly increased after 4 weeks of JDP2 overexpression, indicating the development of first-degree atrioventricular block (AVB)." (PMID 33265909, 2020).
behavioral disorders (1 paper, 2024). "Thus, the understanding of how Jdp2 controls the cell cycle and the differentiation of Gabra6+ GCPs into functional PCs through calcium uptake is critical for the development of the use of Jdp2 to treat PC-mediated genetic diseases and related behavioral disorders." (PMID 39695141, 2024).
cervical cancer (1 paper, 2020). A primary or metastatic malignant neoplasm involving the cervix. "Furthermore, both Tm and Th significantly induced JDP2 in human cervical cancer HeLa cells." (PMID 33108704, 2020).
cutaneous melanoma (1 paper, 2022). A primary melanoma arising from atypical melanocytes in the skin. "JDP2 was identified and validated to be a ferroptosis-related gene signature for predicting survival in cutaneous melanoma." (PMID 36275721, 2022).
gastric cancer (1 paper, 2020). A primary or metastatic malignant neoplasm involving the stomach. "The cell reprogramming method that uses OCT4 and JDP2 to generate gastric cancer cells is based on this notion." (PMID 32493501, 2020). "The treatment of gastric cancer cell lines with OCT4 and JDP2 inhibited the tumorigenic function of the cells by switching off BMP7." (PMID 32493501, 2020).
lymph node metastasis (1 paper, 2018). "It has been identified that decreased-expression of JDP2 was related to lymph node metastasis and distant metastasis." (PMID 29713243, 2018).
melanoma (1 paper, 2022). A malignant, usually aggressive tumor composed of atypical, neoplastic melanocytes. "The genes of HAMP, SLC7A5, CYBB, and IFNG were highly expressed in melanoma cell lines, while JDP2, TUBE1, PROM2, GPX2, FBXW7, and ARNTL were lowly expressed in melanoma cell lines." (PMID 35373463, 2022).
osteosclerosis (1 paper, 2022). Abnormally high bone density. "Interestingly, modulation of Jdp2 expression also led to osteosclerosis by affecting osteoclast differentiation." (PMID 35242136, 2022).
ovarian carcinoma (1 paper, 2019). A malignant neoplasm originating from the surface ovarian epithelium. "Therefore, we further examined the correlation of JDP2 levels with clinicopathological characteristics in 146 clinical ovarian cancer samples." (PMID 31434880, 2019). "Furthermore, the effect of JDP2 dysregulation on genotoxic stress was examined using an in vivo intraperitoneal ovarian cancer mouse model treated with Topotecan, a common chemotherapeutic drug widely used to treat ovarian, lung, and other cancers." (PMID 31434880, 2019).
prostate carcinoma (1 paper, 2010). A carcinoma that arises from epithelial cells of the prostate gland. "In addition, prostate cancer cell lines with JDP2 over-expression form smaller tumors in mice." (PMID 20214788, 2010).
Sepsis (1 paper, 2023). Sepsis is defined as life-threatening organ dysfunction caused by a dysregulated host response to infection. "Analysis of transcription factor expression for the DEGs above revealed that Fosl2 and Jdp2, components of the AP‐1 transcription factor complex, were specifically and highly expressed in Hep_Cd9, further supporting its proinflammatory function in response to sepsis." (PMID 37808269, 2023).
Stroke (1 paper, 2025). Sudden impairment of blood flow to a part of the brain due to occlusion or rupture of an artery to the brain. "Since in our animal model, none of the animals exhibited any obvious phenotype during daily scoring, and the mortality rate did not increase under JDP2 overexpression, we assume that there is no severe stroke-prone thrombus formation." (PMID 40710332, 2025).
cancer (31 papers, 2010 to 2025). A tumor composed of atypical neoplastic, often pleomorphic cells that invade other tissues. "Our findings indicate that tumors with elevated expression levels of HEYL, RPS17, and JDP2 are associated with a poorer prognosis for cancer patients." (PMID 39676867, 2024). "ATF3 and JDP2 deficiency in cancer-related fibroblasts enhances tumor growth via SDF-1 transcription." (PMID 36741260, 2023). "Overall, these results suggest that JDP2 has a wide range of functional roles in biological processes and cancer development and progression, but the underlying mechanism is still poorly understood." (PMID 28146118, 2017). "Double deficiency of ATF3 and Jdp2 in mice stromal tumors promotes cancer growth." (PMID 32493501, 2020). "Recent studies of tumor cells have demonstrated that JDP2 is a tumor suppressor, suggesting that genomic alterations might be the underlying cause of cancer development." (PMID 24202329, 2013). "JDP2 has also demonstrates important roles in cell-cycle regulation, cancer development and progression, inhibition of adipocyte differentiation, and the regulation of antibacterial immunity and bone homeostasis." (PMID 38473360, 2024). "Overall, these findings demonstrate the diverse role of JDP2 in many biological processes, especially cancer development." (PMID 38473360, 2024). "Several studies have also demonstrated that JDP2 plays a role in both cancer development and progression." (PMID 38473360, 2024). "Ets1, YY2 and JDP2 all contribute to cancer cell proliferation, invasiveness, EMT, drug resistance and neo-angiogenesis by regulating gene transcription." (PMID 36497433, 2022). "JDP2, has been used as a pluripotency-promoting factor in the reprogramming of cancer cells to reduce their cancerous features." (PMID 32493501, 2020). "One possible mechanism by which JDP2 expression in BMDCs contributes to metastasis is by regulating the secretion of soluble factors that affect cancer cell metastatic properties." (PMID 26497998, 2015). "Taken together, these results suggest that JDP2 expression within the host BMDCs plays a determinant role in cancer progression and metastasis." (PMID 26497998, 2015). "Collectively, JDP2 expression within the cancer cells plays a dichotomous role in cancer progression." (PMID 26497998, 2015). "Our results provide evidence that JDP2 plays a critical role in the cellular adaptive response to ROS and electrophiles generated by various cellular stimuli and in the generation of cancer progenitor cells with the phenotypes of stem cells and cancer cells." (PMID 24202329, 2013). "In conclusion, we cannot generate the iPSCs from DAOY meddullobastoma cells, instead we generated the iPCCs which have higher potency to generate the cancer-inducing ability than the original DAOY cells by JDP2 and OCT4." (PMID 24202329, 2013). "JDP2 acts as an AP-1 repressor protein to suppress cell proliferation during cancer progression and participates in the maintenance of ROS homeostasis to prevent cell damage by ROS." (PMID 24202329, 2013). "It is has been reported that JDP2 plays an important role in cancer development and progression." (PMID 35584452, 2022). "SMARCD3, BRD9, JDP2, were also reported to be a oncogene role in some cancer." (PMID 36506326, 2022). "For example, JDP2 can promote cancer cell growth in leukemia and hepatocellular carcinoma but may also be a tumor suppressor in cancer cells." (PMID 32493501, 2020). "This method is a good example of a therapeutic strategy that might restrict cancer progression by using JDP2 together with OCT4 as reprogramming factors." (PMID 32493501, 2020).